VPS4A (vacuolar protein sorting 4 homolog A)
Description:
Involved in late steps of the endosomal multivesicular bodies (MVB) pathway. Recognizes membrane-associated ESCRT-III assemblies and catalyzes their disassembly, possibly in combination with membrane fission. Redistributes the ESCRT-III components to the cytoplasm for further rounds of MVB sorting. MVBs contain intraluminal vesicles (ILVs) that are generated by invagination and scission from the limiting membrane of the endosome and mostly are delivered to lysosomes enabling degradation of membrane proteins, such as stimulated growth factor receptors, lysosomal enzymes and lipids. It is required for proper accomplishment of various processes including the regulation of endosome size, primary cilium organization, mitotic spindle organization, chromosome segregation, and nuclear envelope sealing and spindle disassembly during anaphase. Involved in cytokinesis: retained at the midbody by ZFYVE19/ANCHR and CHMP4C until abscission checkpoint signaling is terminated at late cytokinesis. It is then released following dephosphorylation of CHMP4C, leading to abscission. VPS4A/B are required for the exosomal release of SDCBP, CD63 and syndecan. Critical for normal erythroblast cytokinesis and correct erythropoiesis. (Microbial infection) In conjunction with the ESCRT machinery also appears to function in topologically equivalent membrane fission events, such as the terminal stages of cytokinesis and enveloped virus budding (HIV-1 and other lentiviruses).
Synonyms: VPS4; VPS4-1; FLJ22197; SKD2; SKD1; SKD1A; CIMDAG
Tractability: Antibody: its Gene Ontology location is reachable by antibodies, with high confidence; UniProt places it where antibodies can reach, with medium confidence. PROTAC: ubiquitination databases record sites on it; its protein half-life has been measured.
Gene: Protein-coding gene on chromosome 16 (69,311,336 to 69,326,939, forward strand). Ensembl gene ENSG00000132612.
Subcellular location: Late endosome membrane; Midbody; Cytoplasm, cytoskeleton, spindle
Subcellular location (Human Protein Atlas): Midbody
Pathways (Reactome):
Disease: Budding and maturation of HIV virion; HCMV Late Events
Cell Cycle: Sealing of the nuclear envelope (NE) by ESCRT-III
Vesicle-mediated transport: Endosomal Sorting Complex Required For Transport (ESCRT)
Gene Ontology:
Molecular function: ATP binding; ATP hydrolysis activity; ATP-dependent protein disaggregase activity; protein binding; protein-containing complex binding
Biological process: cell division; endosomal transport; endosomal vesicle fusion; endosome transport via multivesicular body sorting pathway; intracellular cholesterol transport; membrane fission; midbody abscission; mitotic cytokinesis checkpoint signaling; mitotic metaphase chromosome alignment; negative regulation of cytokinesis; nucleus organization; positive regulation of exosomal secretion; positive regulation of viral budding via host ESCRT complex; protein targeting to lysosome; regulation of protein localization; regulation of protein localization to plasma membrane; vesicle budding from membrane; vesicle uncoating; vesicle-mediated transport; viral budding from plasma membrane; viral budding via host ESCRT complex; viral release from host cell; actomyosin contractile ring contraction; autophagosome maturation; autophagy; and 16 more
Cellular component: centrosome; cytoplasm; cytosol; early endosome; endosome; endosome membrane; extracellular exosome; Flemming body; late endosome; lysosome; midbody; nucleus; perinuclear region of cytoplasm; plasma membrane; spindle pole; vacuolar membrane; ATPase complex; late endosome membrane; nuclear pore; spindle
Genetic constraint (gnomAD): Loss-of-function variants: 20 observed, 49.72 expected, observed/expected ratio (o/e) 0.4, 90% interval 0.28 to 0.58. The synonymous counts are far from expectation, so gnomAD's model fits this gene poorly and the ratio says little. Missense variants: 419 observed, 564.19 expected, observed/expected ratio (o/e) 0.74, 90% interval 0.69 to 0.81. Synonymous variants: 293 observed, 224.69 expected, observed/expected ratio (o/e) 1.3, 90% interval 1.18 to 1.44.
Homologues: Orthologues: chimpanzee VPS4A (100% identical), mouse Vps4a (99% identical), rat Vps4a (99% identical), dog VPS4A (99% identical), guinea pig VPS4A (98% identical), pig VPS4A (98% identical), tropical clawed frog vps4a (90% identical), zebrafish vps4a (84% identical), Drosophila melanogaster Kat60 (35% identical), Drosophila melanogaster kat-60L1 (34% identical), Caenorhabditis elegans figl-1 (33% identical), Drosophila melanogaster Fign (32% identical), and 1 more. Paralogues in human: VPS4B (81% identical), KATNAL1 (36% identical), KATNA1 (36% identical), SPAST (35% identical), KATNAL2 (34% identical), FIGNL1 (34% identical), FIGN (27% identical), ATAD1 (26% identical), FIGNL2 (22% identical).
Diseases named in the same sentence as VPS4A in open-access papers:
VPS4A is named in the same sentence as 53 diseases in open-access papers, as found by Europe PMC text mining. Sharing a sentence is not in itself a finding about the gene and the disease. The quoted sentences say what the papers report.
hepatocellular carcinoma (13 papers, 2019 to 2025). A malignant tumor that arises from hepatocytes. "Hepatocellular carcinoma cells (HCC) overexpressing Vps4A caused elevated exosomal levels of miR-27b-3p and miR-92a-3p, which are both known oncomiRs." (PMID 32331346, 2020). "VPS4A acts as a tumor suppressor by regulating the secretion and uptake of extracellular miRNAs in human hepatocellular carcinoma cells." (PMID 39698112, 2024). "Research by Lin H et all indicated, a decrease in miR-4454 can promote Vps4A and Rab27A expressions, which then induce exosome secretion and enhance the miR-4454 content in exosomes, thus accelerating the progression of liver carcinoma." (PMID 37404768, 2023). "Meanwhile, overexpression of Vps4A in hepatocellular carcinoma (HCC) cells induced the selection of exosomal miR-193a-3p, miR-320a, miR-132-3p, miR-27b-3p and miR-92a-3p, probably through PI3K/Akt axis." (PMID 35592419, 2022). "Changes in mRNA or protein abundance of VPS4A or VPS4B were reported in hepatoma, breast, and non‐small‐cell lung cancer." (PMID 31930723, 2020). "In addition, VPS4A repressed growth and invasion in hepatocellular carcinoma, acting as a tumor suppressor." (PMID 31861273, 2019). "The silence of both CHMP4B and Vps4A decrease the level of exosomal β-catenin, thus dampening β-catenin signing so as to prevent epithelial–mesenchymal transition (EMT) in hepatocellular carcinoma (HCC)." (PMID 34661500, 2021).
viral infection (6 papers, 2017 to 2025). "Consistent with a central role for VPS4 in several viral infections, we proceed to evaluate the impact of silencing VPS4A in ASFV infection." (PMID 38125905, 2023). "The protein levels of these ESCRT subunits (HRS, VPS28, VPS25, CHMP2B, CHMP4B, CHMP7, VPS4A and ALIX) in the VRC were significantly increased by the viral infection in a dose-dependent manner." (PMID 35120190, 2022). "Two types of VPS4 complexes, VPS4A and VPS4B, have been identified in mammals, and they play important roles in cell biology and disease, including cell division, membrane fusion and fission, and viral infection among other biological processes." (PMID 37869652, 2023). "Changes in the level of VPS4A did not impair ASFV infectivity at early stages; therefore, VPS4A silencing suggests an implication for a later stage in viral infection." (PMID 38125905, 2023).
colon carcinoma (2 papers, 2020 to 2025). "In these experiments, we used CT‐26 cells, a mouse colon carcinoma line that was transiently transfected by siRNA targeting mouse Vps4a and Vps4b (Fig EV5A and B)." (PMID 31930723, 2020). "Potentially, this could explain the re-sensitization of the colon cancer cells to Oxa after VPS4A knockdown." (PMID 40558556, 2025). "First, we confirmed that silencing of Vps4a and Vps4b in mouse colon cancer cells recapitulated the synthetic lethality observed in human CRC cells, such that it was accompanied by activation of caspase 7 and canonical NF‐κB signaling leading to cell death (Fig EV5B and C)." (PMID 31930723, 2020). "Finally, we believe that cell death induced by VPS4A+B depletion may stimulate not only adaptive but also innate immune responses, because the conditioned medium from dying Vps4a+b‐depleted mouse colon carcinoma cells induced an anti‐tumor M1 phenotype in mouse macrophages." (PMID 31930723, 2020).
dyserythropoietic anemia (2 papers, 2023 to 2024). "Two independent studies have demonstrated that individuals carrying single mutations in the VPS4A gene developed dyserythropoietic anemia and severe neurodevelopmental delays." (PMID 38687820, 2024).
heart failure (2 papers, 2014 to 2023). Inability of the heart to pump blood at an adequate rate to meet tissue metabolic requirements. "In 3 months old mice, Western blot analysis showed that Vps4a protein levels were significantly decreased in Vps4afl/fl Myh6 mice compared to Vps4afl/fl mice, while the expressions of markers for heart failure, such as p-AKT and Myh7, increased." (PMID 37445978, 2023). "Together, these data suggested that cardiomyocyte-specific Vps4a knockout mice developed a progressive cardiac dysfunction which eventually led to heart failure." (PMID 37445978, 2023). "To define the cellular role of increased VPS4a in heart failure, we overexpressed VPS4a in HEK 293T cells and showed a significant decrease in cell number." (PMID 25033200, 2014). "Once the autophagic flux was blocked by knockout Vps4a, accumulation of ubiquitinated proteins, vacuole formation, myofibrillar disarray, and enhanced intermuscular fibrosis led to contractile dysfunction, cardiac hypertrophy, and heart failure." (PMID 37445978, 2023). "Although the presence of the SNP, rs16958754, interfered with miR-16 interaction with VPS4a, the MAF of this SNP in our two heart failure cohorts was rare (0.7 and 2.2%)." (PMID 25033200, 2014).
adenoma (1 paper, 2020). A neoplasm arising from the epithelium. "In contrast, in the same samples, we detected no change in the level of VPS4A mRNA between normal colon, adenoma, and CRC (Fig EV1A)." (PMID 31930723, 2020).
congenital dyserythropoietic anemia (1 paper, 2024). Congenital dyserythropoietic anemia (CDA) is a heterogenous group of hematological disorders of late erythropoiesis and red cell abnormalities that lead to anemia. "Mutations in the human AAA-ATPase VPS4 isoform, VPS4A, cause severe neurodevelopmental defects and congenital dyserythropoietic anemia (CDA)." (PMID 38687820, 2024). "First, mutations in VPS4A in patients carrying normal VPS4B caused severe diseases associated with structural brain abnormalities, neurodevelopmental defects, cataract, growth defects, and congenital dyserythropoietic anemia (CDA)." (PMID 38687820, 2024).
diabetes (1 paper, 2021). "After performing the dimension reduction from the 24 overlapping DEPs from discovery and validation datasets, a 4-protein classifier (SERPINA5, VPS4A, CP, TF) could distinguish diabetes from DKD3." (PMID 34963468, 2021). "Moreover, a 4-protein (SERPINA5, VPS4A, CP, TF) classifier was built to predict early stage DKD3 from diabetes." (PMID 34963468, 2021).
endometrial carcinoma (1 paper, 2025). A malignant tumor arising from the epithelium that lines the cavity of the uterine body. "In our previous study, CHMP4B and VPS4A mitigate GSDMD-mediated pyroptosis by promoting cell membrane remodeling in endometrial carcinoma." (PMID 40538398, 2025).
Flavivirus Infections (1 paper, 2023). Infections with viruses of the genus FLAVIVIRUS, family FLAVIVIRIDAE. "A plausible reason for this finding could be a functional redundancy between VPS4A and VPS4B that would compensate for the lack of VPS4A at particular infection stages, as has previously been described for other ESCRT components such as CHMP2 or CHMP4 families in flavivirus infection." (PMID 38125905, 2023).
glioma (1 paper, 2024). A benign or malignant brain and spinal cord tumor that arises from glial cells (astrocytes, oligodendrocytes, ependymal cells). "We found significant differences in the expression levels of ADD2, CTC1, SRCIN1, RORA, and ULK2 genes in gliomas of different grades, excluding VPS4A." (PMID 39698112, 2024). "Furthermore, survival analysis revealed that patients with glioma with high expression of ADD2, CTC1, SRCIN1, VPS4A, ULK2, excluding RORA, had a longer overall survival than those with low expression." (PMID 39698112, 2024). "Similarly, disease-free survival was found to be longer in patients with glioma with high expression of ADD2, CTC1, SRCIN1, RORA, VPS4A, and ULK2 than in those with low expression." (PMID 39698112, 2024).
HCMV infection (1 paper, 2024). "The pUL71 vMIM2 is necessary and sufficient to recruit VPS4A to juxtanuclear structures in co-transfected cells and is necessary for VPS4A recruitment to pUL71-positive structures that have been identified as sites of virus assembly during HCMV infection." (PMID 38900818, 2024). "We sought to recapitulate these findings and investigated whether accumulation of VPS4A at the cVAC is a general feature of HCMV infection." (PMID 38900818, 2024). "Localisation of VPS4A to the cVAC during HCMV infection has been shown previously." (PMID 38900818, 2024).
hypertrophy (1 paper, 2023). Hypertrophy is the increase in the volume of an organ or tissue due to the enlargement of its component cells. "Vps4a knockout mice displayed conspicuous cardiac hypertrophy at 4 months." (PMID 37445978, 2023). "Similarly, deletion of Vps4a in the heart also led to left ventricular dilation, decreased systolic function, cardiac hypertrophy, impaired cardiomyocyte structure with vesicular accumulation, and compromised mitochondrial arrangement." (PMID 37445978, 2023).
Intellectual disability (1 paper, 2020). "Interestingly, VPS4A is known to directly interact in humans with an intellectual disability gene, CHMP1A, from nuclear magnetic resonance, affinity chromatography, pull down and two hybrid assays, and both are part of the necroptosis and endocytosis pathways." (PMID 32005800, 2020). "De novo variants in VPS4A were detected in two unsolved, 100KGP intellectual disability cases but not in any of the other 18,000 cases representing most types of rare disease." (PMID 32005800, 2020).
neuroblastoma (1 paper, 2017). Neuroblastoma (NB) is the most common solid, extracranial childhood tumor. "In order to model the effect of dysfunctional ESCRT-dependent MVBs on Aβ accumulation, a dominant negative, E228Q ATPase-deficient form of VPS4A (dnVPS4A) was expressed for 24 h in N2a neuroblastoma cells harbouring stably transfected human Swedish mutant APP." (PMID 28835279, 2017).
non-small cell lung carcinoma (1 paper, 2025). A group of at least three distinct histological types of lung cancer, including non-small cell squamous cell carcinoma, adenocarcinoma, and large cell carcinoma. "With this in mind, a small molecule, Alo, which was identified as a novel autophagy inhibitor that triggers tumor cell death by targeting VPS4A in both in vitro and in vivo non-small cell lung cancer models, was utilized." (PMID 40558556, 2025).
omphalocele (1 paper, 2020). Omphalocele is an embryopathy classified in the group of abdominal celosomias and is characterized by a large hernia of the abdominal wall, centered on the umbilical cord, in which the protruding viscera are protected by a sac. "Homozygous Vps4a E18.5 embryos are smaller than wild types (WTs), with abnormal body curvature, omphalocele, small and compressed heart, abnormal spinal cord curvature and abnormal brain development." (PMID 32005800, 2020).
tumor (24 papers, 2009 to 2026). "In HCC, Vps4A which was associated with endosomal transport function in cell biology is regarded as tumor suppressor." (PMID 29642941, 2018). "Furthermore, the vacuolar protein sorting-associated protein 4A (Vps4A), which is implicated in intracellular protein trafficking, regulate the release and uptake of exosomes containing both oncogenic and tumor suppressor miRNAs." (PMID 39599900, 2024). "Lower Vps4a level is also associated with poorer prognosis and tumor progression." (PMID 31466358, 2019). "Tumor cells often lose one VPS4 paralog (VPS4A or VPS4B), making them dependent on the remaining enzyme and creating a potential therapeutic vulnerability." (PMID 42032367, 2026). "It was observed that VPS4A was highly expressed in the tumor epithelium for all nine patients compared to the surrounding tissue, with immunolabeling seen in the cytoplasmic compartment." (PMID 40558556, 2025). "For patients where normal intestinal epithelium was also present in the samples, it was seen that there was a lower expression of VPS4A in this tissue compared to the areas of the tumor." (PMID 40558556, 2025). "PI3K-Akt pathway, which has a key role in tumor progression and distant metastasis, is suppressed via HCC-derived EV-vacuolar protein sorting-associated protein 4A (Vps4A)." (PMID 40650114, 2025). "al found that in immunocompromised NU/J mice, injection of HCT116 cells with the knockout of VPS4B and doxycycline (Dox)‐inducible VPS4A‐targeting shRNA expression (HCT116 VPS4B −/− shVPS4A) inhibits tumor growth in mouse." (PMID 37404768, 2023). "In tumor cells, knockout of Vps4b led to an increased expression of Vps4a to compensate for these functions." (PMID 37445978, 2023). "Vps4A is found to facilitate the incorporation of oncogenic miRNAs into EVs, and the authors concluded that Vps4A is a tumor suppressor." (PMID 37508544, 2023). "Wei and colleagues showed that Vps4A inhibited EV function by selectively packaging oncogenic miR-27b-3p and miR-92a-3p into EVs and accumulating tumor-suppressive miR-193a-3p, miR-320a, and miR-132-3p in HCC cells." (PMID 34207985, 2021). "They found that VPS4A is essential in cancers with VPS4B loss adjacent to SMAD4 on chromosome 18q, and VPS4B is required in tumours with co‐deletion of VPS4A and CDH1 (E‐cadherin) on chromosome 16q." (PMID 34254730, 2021). "Vps4A (vacuole protein sorting 4), a member of the AAA-ATPases (ATPases associated with a variety of cellular activities), was recognized as a tumor suppressor in HCC cells by regulating the release and uptake of EV-derived microRNAs." (PMID 34207985, 2021). "In summary, we revealed that VPS4A+B synthetic lethal phenotype of dying cells is accompanied by exposure and secretion of molecules governing inflammatory and anti‐tumor response." (PMID 31930723, 2020). "HCC cells overexpressing Vps4A also resulted in elevated levels of miR-193a-3p, miR-320a, and miR-132-3p, which are all known tumor suppressor miRNAs." (PMID 32331346, 2020). "More research needs to be conducted to determine the exact mechanism that Vps4A uses to sort miRNAs into EVs as well as determine its regulation over tumor growth." (PMID 32331346, 2020). "We also identify the molecular consequences of perturbing VPS4 in cancer cells and propose that inflammatory cell death triggered by VPS4A+B depletion can evoke an anti‐tumor response." (PMID 31930723, 2020). "The overexpression of Vps4A inhibits tumor proliferation, migration, and invasion in vitro and tumor formation in vivo." (PMID 31466358, 2019). "A comparison of Vps4A expression between tumor tissues and adjacent normal tissues revealed that Vps4A is down-regulated in tumor samples." (PMID 31466358, 2019). "After treatment with exosomes from SMMC-7721 cells, Vps4A increased the uptake of tumor suppressor miRNAs by exosomes in HCC cells." (PMID 29642941, 2018).